SLC2A1 (solute carrier family 2 member 1)
Diseases named in the same sentence as SLC2A1 in open-access papers (continued):
Sharing a sentence is not in itself a finding about the gene and the disease.
epilepsy (continued). "They found mutations in SLC2A1 in six patients; five with absence epilepsy and one from the unspecified epilepsies, intellectual disability, and/or movement disorders group." (PMID 28507422, 2017). "Most patients with heterozygous SLC2A1 mutations exhibit GLUT1-deficiency syndrome characterized by low CSF-to-blood glucose ratios together with epilepsy, developmental delay, microcephaly, ataxia, and PxD." (PMID 27891564, 2017). "Investigators from the Danish Epilepsy Center the frequency of SLC2A1 mutations in a cohort of patients with different types of epilepsies." (PMID 28507422, 2017). "Absence epilepsy and paroxysmal dyskinesia co-occur in some patients with SLC2A1 mutations as part of the GLUT1 deficiency syndrome spectrum." (PMID 26132164, 2015). "Here, patients with the SLC2A1 mutation who have movement disorders and epilepsy are described." (PMID 40943684, 2025). "Functional mutations in the GLUT1 gene (SLC2A1) are associated with human epilepsy." (PMID 40507093, 2025). "Therefore, LOF mutation caused by SLC2A1 gene mutation is associated with the occurrence of epilepsy and other symptoms in patients with GLUT1-DS." (PMID 39092009, 2024). "In this study, SLC2A1 variants were identified in 16 epilepsy cases." (PMID 40217381, 2024). "Pathogenic variants in the SLC2A1 gene cause Glucose Transporter 1 deficiency and decreased glucose concentration in the central nervous system leading to a variety of severe neurological symptoms, including ID, epilepsy, and dystonia." (PMID 36674629, 2023). "Patients with mutations in SLC2A1 may have a combination of neurodevelopmental disabilities (e.g., intellectual disability, developmental delay, attentional issues), epilepsy, and movement disorders (spasticity, hypotonia, ataxia, dystonia, and chorea)." (PMID 33833732, 2021). "GLUT1 deficiency syndrome is a treatable disorder of glucose transport into the brain caused by a variety of mutations in the SLC2A1 gene which are the cause of different neurological disorders also with different types of epilepsy and related clinical phenotypes." (PMID 29303961, 2018). "It has been demonstrated that the embryonic lethality of homozygous SLC2A1−/− knockout mice model, whereas the heterozygous SLC2A1+/− mice model could mimic the features of people with GLUT1 deficiency syndrome, causing brain development delay, epilepsy, cognitive dysfunction, and so on." (PMID 38747733, 2024). "Therefore, clinically more attention should be paid to mild epilepsies caused by SLC2A1 variants." (PMID 40217381, 2024). "Importantly, it should be noted that mutations in another member of the SLC2 family, i.e., SLC2A1 (encoding the glucose transporter type 1), are associated with a variety of distinct epilepsy syndromes, e.g., early onset absence epilepsy, childhood absence epilepsy, and myoclonic-atonic epilepsy." (PMID 36873106, 2023). "Since SLC2A1 mutations cause a highly pleomorphic disease, the neurodevelopmental aspects, epilepsy, and chronic motor disturbances (spasticity, dystonia, or ataxia), may overshadow milder manifestations like isolated PED—likely to be underreported both in the literature and clinical practice." (PMID 33833732, 2021). "In SLC2A1, the gene related to GLUT1 deficiency syndrome, we identified a novel missense variant c.74A>G in Patient 19, who was diagnosed with epilepsy, paresis, and dystonia." (PMID 36674629, 2023). "During the last decade, with the candidate gene approach, only few epilepsy-associated genes were reported, such as GABRA1, SLC2A1, CACNA1H and EFHC1, of which the latter two remain debatable." (PMID 40217359, 2023). "In subsequent genes, SLC2A1 and PPP2CA, related to ID and epilepsy, we found another de novo, pathogenic variants." (PMID 36674629, 2023). "For example, EA and epilepsy associations include EA1 (KCNA1), EA2 (CACNA1A), EA5 (CACNB4), EA6 (SLC1A3), SCN2A, KCNA2, ATP1A3, SLC2A1, and PRRT2." (PMID 37008993, 2023).
epilepsy (continued). "Other genetic causes of the PNKD phenotype frequently co-occur with epilepsy, such as the cited PKD (e.g., PRRT2) or PED due to SLC2A1 mutations." (PMID 33833732, 2021). "Seven patients with epilepsy were on a KDT for more than 2 years (3 SLC2A1(+)), all of them had 90–100% improvement, and 3 of them were on a KDT for 6 years or more." (PMID 33806661, 2021). "The age at the onset of symptoms was lower in our patients with epilepsy and in the SLC2A1 (+)-group, and the time from debut to the onset of treatment was significantly higher." (PMID 33806661, 2021). "Median age at debut was lower in the SLC2A1(+)-group (1.7 ± 1.7 versus 2.2 ± 2.2 years), and in the epilepsy group (1.8 ± 1.5 versus 2.7 ± 3.2 years)." (PMID 33806661, 2021). "Although the differences were not statistically significant, the median age at the onset of KDT was higher in SLC2A1(+)-group (8.8 versus 4.9 years), and in the epilepsy group (4.5 versus 3.5 years)." (PMID 33806661, 2021). "In nine families with PED and epilepsy, mutations were found in the SLC2A1 gene encoding the glucose transporter GLUT1." (PMID 22752065, 2013). "Developmental and epileptic encephalopathies (DEE/EEs) are characterized by early onset of seizures, therapy resistance, neurodevelopmental delay, for example, as seen in channelopathies (e.g., GRIN2A-, SCN2A-, SCN1A-, and SCN8A-related epilepsies) or in metabolic conditions (e.g., SLC2A1)." (PMID 38125836, 2023). "Other genetic epilepsies that can benefit from precision therapy include KCNQ2 (carbamazepine, phenytoin), GLUT1 deficiency, SLC2A1 or CDKL5 (ketogenic diet), PCDH19 (clobazam), mutations in KCNQ2, SCN2A, and SCN8A (ion sodium channel blockers), and mTORopathies (mTOR inhibitors)." (PMID 36980114, 2023). "Of particular interest are the glucose transporters SLC2A1 from the SLC2 subfamily; GLUT1 mutations are associated with GLUT1 deficiency syndrome (GLUT1DS1 and GLUT1DS2), and some forms of spasticity (Dystonia-9) and epilepsy (EIG2) (Klepperet al., 2016;Monginet al., 2016)." (PMID 39886335, 2019). "Subjects with an epileptic phenotype caused by SLC2A1 mutation and coding for Glucose Transporter Type 1 (GLUT-1) that prevents a correct glucose share to the CNS, represent a tangible example of the great potentiality of pharmacogenomics in epilepsy treatment." (PMID 31366017, 2019). "Furthermore, two patients with genetically confirmed GLUT1DS had siblings with a similar type of epilepsy but without SLC2A1 gene mutations." (PMID 26933557, 2015). "No doubt this wide variation in clinical presentation contributed to the erroneous assignation of DYT9 (paroxysmal choreoathetosis with spasticity) and DYT18 (PED with or without epilepsy) as two separate conditions; it is now known that the causative gene in both cases was, in fact, SLC2A1." (PMID 23775978, 2013). "The usual suspects for epilepsy, namely brain derived neurotrophic factor (BDNF) detected from the neurotrophin and solute carrier family 2 member 1 (SLC2A1/GLUT1) from the cancer pathway are highlighted via this approach." (PMID 30735541, 2019). "Further analysis conducted on ATP1A2, SLC2A1, SLC2A2 KCNMA1 and KCNN3 showed they all are related to epilepsy or seizures." (PMID 27984588, 2016).
epilepsy (continued). "Monogenic epilepsies can be characterized according to the gene function affected: Impaired function of ion channels (e.g., CACNA1A), receptors (e.g., GABRB3), transporters (e.g., SLC2A1), synapse-related (e.g., PRRT2), and other pathways (e.g., CDKL5, PCDH19) are associated with epilepsy." (PMID 38125836, 2023). "Thirty-five patients manifested epilepsy without any other comorbidity and seven of them (20.0%) carried variants in six genes, namely KCNQ2, NALCN, PAK3, PRRT2, SCN1A, and SLC2A1 that are among the well-known genes causing epilepsies or syndromes including epilepsy." (PMID 36035117, 2022).
diabetes (113 papers, 2007 to 2025). "Thereafter, we tested the association between the SLC2A1 variants and the risk of diabetes leading to nephropathy." (PMID 30353771, 2018). "A more recent genetic association study in Brazilian patients with type 1 diabetes mellitus and inadequate blood glucose control showed that another variant of SLC2A1 (rs3820589) is associated with progression of nephropathy." (PMID 30353771, 2018). "Although the XbaI polymorphism of SLC2A1 is a well-known polymorphism in diabetes, the association between diabetic nephropathy and the XbaI polymorphism in the SLC2A1 gene has been controversial in several case-control studies." (PMID 20540786, 2010). "(2013) provides strong evidence for Asians and marginal evidence for Caucasians, that the rs841853 variant of SLC2A1 may confer increased susceptibility to type 2 diabetes mellitus." (PMID 30353771, 2018). "Interestingly, the SLC2A1 TT and APEX1 TT genotypes are risk alleles associated with the clinical outcome of several diseases, including diabetes and other malignancies." (PMID 20540786, 2010). "Finally, future meta-analysis of multiple studies may overcome the deficiency of small power and to provide more conclusive evidence for the implication of SLC2A1 in complications in diabetes." (PMID 30353771, 2018). "There were two studies (out of five) concerning type 2 diabetes mellitus, which included non-Caucasian populations, one in Asians and one in Tunisians, and both showed a positive association between diabetic nephropathy and SLC2A1 variants." (PMID 30353771, 2018). "We identified 8 hub genes (JUN, ATF3, VEGFA, SLC2A1, HK2, PTGS2, PFKFB3, and KLF6) that were enriched in response to hypoxia, angiogenesis, vasculogenesis, hypoxia-induced signaling, cancer, diabetes, and transplant-related disease pathways." (PMID 36482897, 2022). "CAMK1, GLUT1/SLC2A1 and GLUT3/SLC2A3 genes were involved in glucose and insulin metabolism that played vital role in development of obesity and diabetes." (PMID 29876008, 2018). "SLC2A1 (GLUT1) and SLC2A3 (GLUT3) genes were involved in glucose and insulin metabolism which played vital role in development of obesity, diabetes and CRC." (PMID 29876008, 2018). "HK3, FCN1,CAMK1, GLUT1/SLC2A1 and GLUT3/SLC2A3 are involved in glucose and insulin metabolism that played vital role in development of obesity and diabetes." (PMID 29876008, 2018). "Glucose transporter 1 (or GLUT1), also called the solute carrier family 2, facilitated glucose transporter member 1 (SLC2A1) and thioredoxin-interacting protein (TXNIP) located on chromosome 1 are notable candidate genes for T2D diabetes." (PMID 35164795, 2022). "SLC2A1, SLC2A2 and SLC2A5 gene expression in mid-jejunal mucosa was measured to investigate whether intestinal glucose transporters could be influenced by diabetes, diet and/or metformin-pioglitazone medication and as such have an effect on the postprandial plasma glucose concentrations." (PMID 34669714, 2021).
pancreatic cancer (106 papers, 2010 to 2025). "Solute carrier family 2 member 1 (SLC2A1), commonly referred to as glucose transporter protein type 1, has been consistently associated with the occurrence and prognosis of pancreatic cancer in numerous studies 35-37." (PMID 38370379, 2024). "Furthermore, based on data reported in the Human Protein Atlas database, AP2A2, PLST, PLSI, BLVRB and SLC2A1 were associated with poor 5-year overall survival in pancreatic cancer." (PMID 33048956, 2020). "For example, FoxD1 can promote SLC2A1 (Solute carrier family 2 member 1) transcription and inhibit the degradation of SLC2A1 to facilitate the proliferation, invasion, and metastasis of pancreatic cancer cells." (PMID 39057213, 2024). "Overexpressed pancreatic cancer receptors include SLC2A1, MET, IL1RAP, NPR3, GABRP, SLC6A6, and TMPRSS4." (PMID 35359382, 2022). "The L5 proteins of 3 serotypes of adenovirus HAdV2, HAdV3, and HAdV5 are docked with the seven highly expressed pancreatic cancer receptors SLC2A1, MET, IL1RAP, NPR3, GABRP, SLC6A6, and TMPRSS4." (PMID 35359382, 2022). "SLC2A1 can be used as a biomarker for the diagnosis and treatment of esophageal carcinoma, pancreatic carcinoma patients." (PMID 35830566, 2022). "Many researchers have reported the overexpression of the SLC2A1 gene in patients with pancreatic cancer compared to normal controls." (PMID 33783998, 2021). "The prognostic value of this gene has been studied, and the results indicate that the expression of SLC2A1 is negatively correlated with the prognosis of patients with pancreatic cancer." (PMID 33783998, 2021). "One gene, SLC2A1, is present in five tumor entities (renal, urothelial, lung, liver and pancreatic cancer) and PLS3, SLC16a1, and SLC16A3 are present in four tumor entities." (PMID 32599841, 2020). "SLC2A1 is a prognostic protein for pancreatic cancer patients." (PMID 39311766, 2024). "In some studies, high expression of SLC2A1 is related to worse survival in pancreatic cancer." (PMID 36006549, 2022). "For example, it promotes growth, invasion, and metastasis in pancreatic cancer cells by enhancing aerobic glycolysis via dual regulation of SLC2A1, leading to GLUT1 overexpression." (PMID 40999468, 2025). "The high transcription level of SLC2A1 in the PECMS-high group suggests an energy-independent mode of carbohydrate transmembrane transport and energy utilization in the dense matrix of pancreatic cancer." (PMID 36006549, 2022). "IGF2BP2 binds to m6A-modified GLUT1 mRNA, and both m6A readers stabilize GLUT1/SLC2A1 mRNA in pancreatic cancer and CRC." (PMID 36289851, 2022). "We identified 7 highly expressed pancreatic cancer cell surface receptors (MET, NPR3, IL1RAP, SLC2A1, SLC6A6, GABRP, and TMPRSS4) in all the analyzed datasets." (PMID 35359382, 2022). "Among them, the mRNA levels of ADM, C4orf3, ERO1L, FUT11, BNIP3L, NDRG1, KCTD11, SLC2A1, and P4HA1 were increased in pancreatic cancer tissues compared to adjacent pancreatic tissues from TCGA and GTEx database." (PMID 34221996, 2021). "In pancreatic cancer, FOXD1 contributes to cancer development by promoting SLC2A1 transcription." (PMID 40999468, 2025). "Also, in pancreatic cancer, FOXD1 directly stimulates SLC2A1 transcription, suppresses SLC2A1 degradation via an RNA‐induced silencing complex, upregulates GLUT1 expression and ultimately facilitates the growth, invasion and metastasis of pancreatic cancer cells by controlling aerobic." (PMID 39661501, 2024).
Insulin resistance (93 papers, 2009 to 2026). Increased resistance towards insulin, that is, diminished effectiveness of insulin in reducing blood glucose levels. "Not only that, Slc2a1 can also enhance the metabolism of L-leucine and acetylcarnitine in the cancer pathway and the insulin resistance pathway, respectively." (PMID 31286856, 2019). "Specifically, there were quantitative differences between the expressions of IRS1, PIK3R1, SLC2A1, SLC2A3, and SLC2A4 among the patients with GDM during pregnancy and at 1-year postpartum, i.e., in the two studied groups differing in the degree of insulin resistance." (PMID 39684804, 2024).